ICAM1 (intercellular adhesion molecule 1)
Diseases named in the same sentence as ICAM1 in open-access papers (continued):
Sharing a sentence is not in itself a finding about the gene and the disease.
breast carcinoma (continued). "ICAM-1 is a surface transmembrane glycoprotein belonging to the immunoglobulin superfamily of adhesion molecules and plays a role in immune response, but also is involved in mechanisms of invasion and metastasis in breast cancer." (PMID 24344116, 2014). "Moreover, downregulation of ICAM-1 at the protein and mRNA levels strongly inhibited human breast cancer cell invasion." (PMID 23874773, 2013). "Based on these findings, ICAM-1 represents a potential target in breast cancer treatment." (PMID 23874773, 2013). "Ligation of MUC1 and ICAM-1 may represent a mechanism for movement of breast cancer cells through stromal and endothelial tissues." (PMID 21798038, 2011). "Therefore it is important to understand how OPN selectively regulate p70S6K/mTOR phosphorylation leading to NF-κB dependent AP-1 mediated ICAM-1 expression in breast cancer cells." (PMID 20459645, 2010). "In summary, we report that OPN regulates NF-κB mediated ICAM-1 expression in breast cancer cells." (PMID 20459645, 2010). "In this study, we report that purified native OPN induces ICAM-1 expression in breast cancer cells." (PMID 20459645, 2010). "Interestingly, breast cancer cells expressing NDRG2 have also inhibited osteoclast differentiation by downregulating secreted ICAM1 expression, suggesting that NDRG2 may suppress bone metastases from breast cancer." (PMID 38611020, 2024). "Notably, ICAM1 expression levels are higher in TNBC than in the other breast cancer subtypes." (PMID 38907234, 2024). "Interestingly, anti-ICAM1 treatment has been proposed to interfere with tumor progression in multiple myeloma, lung and breast cancer, showing that the targeting of angiocrine factors might be a valid therapeutic option." (PMID 34073394, 2021). "In addition to this, it has recently been shown that overexpression of heparanase promotes the formation of cell clusters in MDA-MB-231 breast cancer cells, most likely by modulating the level of intercellular adhesion molecule 1 (ICAM-1) and phosphorylation status of downstream kinases." (PMID 32984308, 2020). "Thus, the biological significance of ICAM1 expression in breast cancers remains controversial." (PMID 30082828, 2018). "ICAM1 may still be an attractive molecular target for TNBCs, but further investigations elucidating the role of ICAM1 in targeted therapies have to take into consideration selective subtypes of breast cancer." (PMID 30082828, 2018). "MUC1 may contribute to metastasis, as it was demonstrated in vitro that the MUC1 protein can bind to intercellular adhesion molecule-1 (ICAM-1), which facilitates adhesion of breast cancer cells to endothelial cells, leading to adhesion and subsequent migration through the vessel wall." (PMID 24810688, 2014). "Therefore, agents that repress ICAM-1 expression in breast cancer cells and subsequently blocks the interaction between cancer and endothelial cells might be an important therapeutic target for repressing the metastatic potential of cancer cells." (PMID 23874773, 2013). "Thus, blocking OPN-induced ICAM-1 expression through mTOR and p70S6 kinase pathway may act as important target for the control of breast cancer." (PMID 20459645, 2010). "Thus, a better understanding of the molecular mechanism of regulation of ICAM-1 expression in response to OPN may help in developing a novel therapeutic approach for the treatment of breast cancer." (PMID 20459645, 2010). "Thus, the study suggests that blocking of OPN-induced ICAM-1 expression through mTOR/p70S6 kinase signaling may be an important therapeutic target for the management of breast cancer." (PMID 20459645, 2010). "While inhibition of NOTCH signalling increased lung metastasis in neuroblastoma and breast cancer, enhanced NOTCH signalling was reported by us to induce downregulation of endothelial ICAM1 in the liver accompanied by reduced hepatic melanoma metastasis." (PMID 39875968, 2025).
breast carcinoma (continued). "It inhibits the cleavage of the NE extracellular substrates CD40 and ICAM‐1, downregulates NE‐induced ICAM‐1 gene expression, and inhibits the migration of highly invasive MDA‐MB‐231 breast cancer cells." (PMID 40979214, 2025). "Similar findings revealed that LPS‐activated monocytes release TNF‐α to induce endothelial ICAM‐1/VCAM‐1 expression, thereby facilitating breast cancer cell adhesion and metastatic progression." (PMID 40747615, 2025). "To further elucidate the relationship between tumor ICAM1 and MAPK, we established a breast cancer mouse model using shControl and shICAM1 cells." (PMID 38907234, 2024). "In MDA-MB-231 breast cancer cells, EGF induces an increase in levels of ICAM-1, while the EGFR inhibitor reduces ICAM-1 expression." (PMID 39594667, 2024). "ICAM1 expression is exclusive to triple-negative and HER2-positive breast cancer but is induced by proinflammatory cytokines such as TNF–α, IFN–γ, and IL–1β, independent of the tumor hormone receptor status, and is linked to high immune cell infiltration." (PMID 39590296, 2024). "For gene markers in HER2 breast cancers, possible targeting of individual clusters with PLAT, ICAM1, and FGA is observed." (PMID 36598637, 2023). "We found that AQP1 recruited ANXA2 to the Golgi apparatus, promoted Golgi apparatus extension, and induced secretion of ICAM1 and CTSS, which induced breast cancer cell invasion." (PMID 36803413, 2023). "AQP1 can also reside in the Golgi apparatus, where it can induce cell secretion of ICAM1 and CTSS, leading to the local invasion of breast cancer." (PMID 36803413, 2023). "A recent study reported that ICAM1 bound with integrins to activate the epithelial-to-mesenchymal transition process through TGF-β/SMAD signaling, ultimately enhancing breast cancer cell invasion." (PMID 36803413, 2023). "Patients with breast cancer were categorized into 4 groups (luminal A, luminal B, TNBC, and HER-2 over-expressed), as well as the correlation between ICAM1 expression and DFS was analyzed." (PMID 37671167, 2023). "Overexpression of intercellular adhesion molecule 1 (ICAM-1; also known as CD54) and decay acceleration factor (DAF; also known as CD55) in melanoma, multiple myeloma, and breast cancers allows entry of coxsackie viruses into tumor cells." (PMID 37040283, 2023). "By joint analysis of gene expression data from previous studies, we constructed interrelationships of mainly CRHBP, ICAM1, PLAGL1, DNMT1, CNTLN, DKK1, and EGR2 with preterm birth, infant disease, and breast cancer." (PMID 36788602, 2023). "The underlying mechanism was closely related to the upregulation of ICAM-1 expression in HUVECs by Gal-3 and the delivery of ICAM to MDA-MB-231 cells through H-EVs, resulting in the increased metastasis of breast cancer." (PMID 36386163, 2022). "Furthermore, whereas the ability of E0771 cells within primary breast tumors to disseminate and reach the lungs is ICAM-1 independent; once entrapped inside the lung vasculature, ICAM-1 deficient-breast cancer cells but not their control counterparts generate intravascular metastatic lesions." (PMID 35911772, 2022). "For example, Sox2+ breast cancer cells attracted macrophages to the TME by secreting (C-C motif) chemokine ligand 3 (CCL3) and intercellular adhesion molecule 1 (ICAM-1) chemokines." (PMID 36613838, 2022). "The obtained results, when compared to a group of healthy women, indicated a significant increase in ICAM-1 and PECAM-1 serum levels in patients after radical breast cancer treatment." (PMID 35366289, 2022). "In the current study, ICAM-1 and PECAM-1 serum levels were measured as potential biomarkers in 45 female patients in a long-term follow-up period after breast cancer treatment, and compared to 25 age-matched female healthy volunteers." (PMID 35366289, 2022).
breast carcinoma (continued). "In breast cancer, lnc-BM increased JAK2 kinase activity to mediate oncostatin M- and IL-6-triggered STAT3 phosphorylation, promote ICAM1 and CCL2 expression, and mediate macrophage recruitment to the brain and consequently metastasis." (PMID 34123857, 2021). "We utilized three methods to detect CTCs and determine if ICAM1 is clinically relevant to CTC clusters and metastasis in breast cancer." (PMID 34381029, 2021). "In breast cancer cells, Lnc-BM increased the STAT3-dependent expression of ICAM1 and CCL2, which regulated vascular co-option and recruitment of macrophages in the brain, respectively." (PMID 34123857, 2021). "In breast cancer, ICAM-1 is upregulated by TNF-α and it is thought that ICAM-1 is involved in tumor cell invasion and metastasis by promoting intravasation." (PMID 34404457, 2021). "In a follow-up study looking at molecular regulators of extravasation, the same group found that in addition to ICAM-1, MMP-9 and frizzled 4 were found to regulate invasion of bone-metastatic breast cancer cells." (PMID 31936342, 2020). "We found that ICAM1 mRNA expression was higher in TNBC compared with the adjacent normal breast tissue and other types of breast cancer." (PMID 33072116, 2020). "We examined several cell lines of breast cancer and found that MDA-MB-231 and MDA-MB-468 had the highest expression level of ICAM1." (PMID 33072116, 2020). "Short-term microgravity led to an increased synthesis of ICAM-1 and VCAM-1 proteins in MDA-MB-231 breast cancer cells during a parabolic flight campaign." (PMID 32013031, 2020). "Further, our identification of increased IL8, IL6, HAS2, and ICAM1, as well as decreased ERBB2 in MpBC samples matches findings from a microarray comparison of gene expression between metaplastic breast cancers and ductal carcinomas of the breast." (PMID 31488082, 2019). "Both cell adhesion molecules ICAM-1 and VCAM-1 are increased in patients with advanced breast cancer and the increase in VCAM-1 is of prognostic significance." (PMID 31731625, 2019). "The adoptive transfers of γδ and CD8+ T-cells upregulated MHC class I and CD54/ICAM-1 on CSC-like cells and induced antigen specific-killing by CD8+ T-cells in breast cancer." (PMID 30841635, 2019). "In the present study, we evaluated 23 surgically resected tumor biopsies from primary operable breast carcinomas with pair-matched normal tissue samples based on the organization of infiltrating lymphocytes, TLS formation, and ICAM1 expression." (PMID 30082828, 2018). "Additionally, to confirm whether ICAM-1 is post-translationally regulated by ubiquitin-mediated proteasomal degradation in metastatic breast cancer, we blocked proteasome activity by MG132 treatment for 6 h in MDA-MB-231 cells and performed an ubiquitylation assay." (PMID 29137327, 2017). "FBXO4 showed specificity for ICAM-1 and acts as a tumor suppressor for ICAM-1 mediated progressive breast cancer." (PMID 29137327, 2017). "In human breast carcinoma, higher levels of VEGF-C and VEGF-D were seen in ductal carcinomas compared to medullary carcinomas and correlated with decreased ICAM-1 expression and lower numbers of infiltrating lymphocytes." (PMID 28066431, 2016). "It is reported that serum levels of two important adhesion molecules, ICAM1 and VCAM1 are significant higher in patients with colorectal cancer, ovarian cancer, NSCLC and breast cancer." (PMID 26239324, 2015). "In fact, studies showed that inactivation of NFκB in MDA-MB-231 breast cancer cells inhibit the expression of many downstream target genes involved in tumor metastasis such as MMP-2, MMP-9, VEGF, ICAM-1 and uPAR." (PMID 23874773, 2013). "We are unique in investigating the role of MUC1 in the motility of Luminal B breast cancer cell lines, focusing on the binding of MUC1 to ICAM-1." (PMID 21798038, 2011). "Furthermore, the TCGA data set’s ROC curve analysis was utilized to thoroughly assess the sensitivity and specificity of ICAM-1 for TNBC and breast cancer." (PMID 38799250, 2024).
breast carcinoma (continued). "Interestingly, the overexpression of the receptors for intercellular adhesion molecule 1 (ICAM-1) and decay-accelerating factor (DAF) caters to the effective entry of coxsackievirus into breast cancer cells." (PMID 38920716, 2024). "Our present study reported that AQP1 could promote Golgi apparatus extension, leading to increased cell secretion of ICAM1 and CTSS and increasing breast cancer cell migration and invasion." (PMID 36803413, 2023). "Hence, Ig superfamily CAMs are capable of homophilic and heterophilic interaction, and recent work demonstrated the role of homophilic ICAM-1-ICAM-1 interaction in the formation of homotypic tumor cell clusters and lung metastasis of breast cancer cells." (PMID 37173970, 2023). "Cellular secretion of ICAM1 and CTSS led to the migration and invasion of breast cancer cells." (PMID 36803413, 2023). "In fact, ICAM1 has been reported as TNBC markers and acts as prognostic molecule of breast cancer." (PMID 36788602, 2023). "The analysis revealed a significant reliable increase in PECAM-1 and ICAM-1 molecules in patients following breast cancer treatment with depression in comparison to patients without depression." (PMID 35366289, 2022). "Our present findings are therefore consistent with these observations, suggesting that ICAM-1 expression on breast cancer cells and possibly on other solid tumors is not obligatory for CTL-mediated killing." (PMID 35911772, 2022). "Taken together, these results suggest that the eradication of a primary E0771 breast tumor elicited by either Treg depletion or by a tumor vaccine is not facilitated by ICAM-1 expression on the breast cancer cell targets." (PMID 35911772, 2022). "In conclusion, our results provide a first hint that elevated serum levels of ICAM-1 and PECAM-1 could serve as early predictive biomarkers in breast cancer survivors that might help to improve the management of these patients." (PMID 35366289, 2022). "This is also a first indication that the breast tumor expression of ICAM-1 is not required for CTL-mediated killing but can function as a suppressor of intravascular breast cancer metastasis to lungs." (PMID 35911772, 2022). "Molassamide, isolated from the marine cyanobacterium DRTO-73, showed a dual action on the migration of highly invasive MDA-MB-231 breast cancer cells by modulating both elastase-induced intercellular adhesion molecule (ICAM)-1 gene expression and ICAM-1 proteolytic processing by elastase." (PMID 35621924, 2022). "Overexpression of transgelin-2 in cytotoxic CD8+ T cells increases adhesion to ICAM-1-positive E0771 breast cancer cells, but not ICAM-1-negative B16/F10 melanoma cells, suggesting the therapeutic potential of transgelin-2 in T-cell immunotherapy." (PMID 33898417, 2021). "To determine if ICAM1 is a valid target in TNBC and metastasis, we further examined the clinical relevance of ICAM1 expression to patient outcomes by analyzing two independent breast cancer patient cohorts, GSE2505540 and GSE145641." (PMID 34381029, 2021). "In searching for potential molecular targets, we found that intercellular adhesion molecule-1 (ICAM-1), an immunoglobulin superfamily glycoprotein located on the cell surface, is highly expressed in certain types of breast cancer cells (i.e., triple-negative subtypes)." (PMID 35056985, 2021). "Likewise, intercellular adhesion molecule-1 (ICAM1) expression on ECs plays a role in the adhesion of lung carcinoma to ECs, promoting the invasion and metastasis of breast cancer cells and liver metastasis of colorectal cancer cells." (PMID 34073394, 2021). "We found that mouse 4T1 breast cancer cells expressed ICAM-1 while mouse fibroblast L929 cells did not." (PMID 35056985, 2021). "In addition, leptin-dependent activation of JAK1/2/STAT3/FAK/ERK/GSK3αβ signaling cascade in breast tumor cells enhanced the production of intercellular adhesion molecule 1 (ICAM-1), toward the development of breast cancer bone metastasis." (PMID 33562737, 2021).
breast carcinoma (continued). "While ICAM1 is known to interact with β2 integrins in leukocytes, these ligands are not detectable in breast cancer cells." (PMID 34381029, 2021). "For example, high levels of soluble intercellular adhesion molecule 1 (ICAM-1), VCAM-1 and platelet-derived growth factor (PDGF) detectable in the BM plasma of untreated advanced breast cancer patients possibly contribute to DTCs escape out of the blood vessels into the BM." (PMID 31338489, 2019). "Furthermore, osteopontin regulates the ICAM-1 and VEGFA expression mainly in triple-negative/basal-like breast cancer, supporting its role in tumor progression in TNBC." (PMID 31731625, 2019). "Furthermore, previous studies showed that IL-23 increased the abundances of intercellular adhesion molecule-1 and vascular cell adhesion molecule-1 on endothelial cells, and improved the endothelial marker CD31 in mammary cancer." (PMID 30483821, 2019). "Corresponding to changes in patient tissues, of the 100 breast cancer samples, 10 metastatic cancer cells/tissues were negative and 50 were positive in, whereas 40 progressive breast cancer cells/tissues were strongly positive for ICAM-1." (PMID 29137327, 2017). "We observed that metastatic breast cancer cells (MDA-MB-231) showed consistently decreased ICAM-1 stability compared to that in non-metastatic cancer cells (MCF7)." (PMID 29137327, 2017). "Therefore, we examined the relationship between FBXO4 and ICAM-1 as well as the suppressive role of ICAM-1 in the regulation of metastatic progression, which was dependent on FBXO4, in metastatic breast cancer cells." (PMID 29137327, 2017). "In conclusion, we identify membrane-bound ICAM-1 as a major regulator of proinvasive CAF activity in head and neck carcinoma, but a similar role could also be played in lung and breast carcinomas." (PMID 27901489, 2017). "Additionally, using the primary expression data of breast cancer patients from the TCGA database, we drew the overall survival curves for hsa-miR-19b, MYLIP and cell adhesion molecules (E-Cadherin, ICAM-1 and Integrin β1) respectively." (PMID 28969074, 2017). "Whether NF-kB and ICAM-1 establish CRC-CAF adhesion, as shown to be the case in 12(S)-HETE-triggered breast cancer/EC intravasation, needs to be investigated in future studies." (PMID 28013338, 2017). "To confirm that the ICAM-1 is post-translationally controlled in metastatic and non-metastatic breast cancer cells, we first blocked protein synthesis using cycloheximide (CHX)." (PMID 29137327, 2017). "Moreover, we found that the E3 ligase FBXO4 decreases ICAM-1 stability and EMT of metastatic breast cancer cells." (PMID 29137327, 2017). "Interestingly, ICAM-1 appeared overexpressed in CAF isolated from head and neck, lung and breast carcinomas when compared to hDF." (PMID 27901489, 2017). "In this article, we mainly illustrated the regulatory mechanisms of miR-19b promoting breast cancer metastasis through directly targeting MYLIP expression and affecting the expression levels of cell adhesion molecules (including E-Cadherin, ICAM-1 and Integrin β1)." (PMID 28969074, 2017). "To determine the expression and effects of altered ICAM-1 stability on EMT, we measured the post-transcriptional RNA and protein levels of ICAM-1 together with those of EMT markers by RT-PCR and western blotting, and observed clear differences in various subtypes of breast cancer cells." (PMID 29137327, 2017). "To evaluate the characteristics of ICAM-1 expressing cells, we assessed the migratory and invasive characteristics of metastatic and non-metastatic breast cancer cells by analyzing EMT marker expression and invasion and migration assay in." (PMID 29137327, 2017). "ICAM1 expression was reported to determine the malignant potential of cancer, to have a role in the invasion of human breast cancer cells, and upregulated endogenous ICAM-1 reduced ovarian cancer cell growth in the absence of immune cells." (PMID 25521548, 2014).